ADAR (adenosine deaminase RNA specific)
Diseases named in the same sentence as ADAR in open-access papers (continued):
Sharing a sentence is not in itself a finding about the gene and the disease.
cancer (continued). "The conversion of A to I by ADAR results in cancer development." (PMID 33324542, 2020). "Investigators postulate that tumor ADAR1 expression may serve as classifier for therapeutic response and that cancer directed targeting of ADAR 1 may represent a viable approach to sensitization of poorly responsive tumors." (PMID 32650588, 2020). "Thereafter, ongoing studies have been elucidate role of ADAR in cancer development and progression." (PMID 32410589, 2020). "MiRNAs themselves are heavily edited by ADAR enzymes in cancer." (PMID 31847302, 2019). "The intriguing link between RNA editing and gender-related patient OS may suggest a possible contribution of gender-specific transcription factors or sex-dependent hormones controlling ADAR expression/activity at least in cancer." (PMID 30760294, 2019). "Hopefully, in the next decade, ADAR as a target in cancer therapy will become a reality." (PMID 30585209, 2018). "Specifically, because ADAR has been shown to be such an integral player in apoptotic regulation and cellular differentiation, cancer is of especially heightened interest and, in fact, more and more evidence is pointing to dysregulation of the editing process being a major factor in tumorigenesis." (PMID 30197877, 2018). "Notably, MDA5 gene expression and protein levels correlate with ADAR KO-sensitivity across a spectrum of cancer cell lines." (PMID 30575730, 2018). "Taken together with several lines of investigation from ovarian and other cancers the current study suggests that ADARs (and ADAR in particular) may be useful biomarkers for the diagnosis and management of EOC." (PMID 27911851, 2016). "Since RT mono-localize on the genome, they cannot match Alu sequences, which excludes that increased SBS frequencies that were observed in transcripts expressed in cancer or healthy could originate from ADAR editions." (PMID 23137041, 2012). "This interpretation and re-evaluation of the base mechanisms driving somatic mutagenesis is consistent with the original hypothesis that cancer genomes display a “dysregulated AID/APOBEC Ig SHM-like signature” coupled with an ADAR deaminase RNA editing signature and reverse transcription." (PMID 39940758, 2025). "Additionally, converting endogenous RNA to ADAR-target Z-RNA may increase the amount of unbound Z-RNA, which can stimulate cancer cell apoptosis." (PMID 38203521, 2023). "Indeed, ADAR inhibitors are being considered for use in cancer immunotherapy." (PMID 34297039, 2021). "Natural compounds may change the level of ADAR-mediated editing in tumors or play an anticancer role by virtue of the non-editing function of ADARs, which will provide a new research direction for the potential of ADARs in cancer therapy." (PMID 33643923, 2020). "However, increased IFN signaling upon ADAR inhibition in cancer seemed an attractive therapeutic option, as this could overcome immune silencing and potentiate immune checkpoint therapies." (PMID 32380696, 2020). "Beyond their well-established catalytic activity, ADAR enzymes, especially ADAR1, exert several critical editing-independent functions that significantly impact cancer biology." (PMID 40852728, 2025). "The analysis is based on a deaminase-driven reverse transcriptase (DRT) mutagenesis model of cancer oncogenesis involving both the cytosine (AID/APOBEC) and adenosine (ADAR) mutagenic deaminases." (PMID 39940758, 2025). "Upstream sensors like ZBP1, AIM2, and RIPK1, along with regulators identified in cancer-related PANoptosis studies, such as IRF1, ADAR, MAP3K7, and NFS1, were also incorporated for their significant regulatory roles." (PMID 39901195, 2025). "However, the role of APOBEC/ADAR mutations has not yet been clarified in cancer." (PMID 38965255, 2024). "In cancer cells, the protoplasts of CCDC15 (including exon 9) were oncogenic, and ADAR acted as a tumor inhibitor by influencing the growth of cancer cells through binding or catalytic editing, which makes the exon skip." (PMID 38203521, 2023).
cancer (continued). "Correlation analysis between ADAR and ICI expression showed a highly positive correlation in most cancers." (PMID 37414093, 2023). "Notably, very recent study demonstrated that endogenous ADAR-mediated RNA editing can persistently edit the target RNAs with oligonucleotides AIMers in non-human primate liver and has enormous potentials for specific cancer therapies in the nucleic acid-editing level." (PMID 36316318, 2022). "Compared with normal samples, GC cancer samples exhibited obviously higher expression of m6A, m1A and APA writers, but ADAR only showed significantly higher expression in 3 A-to-I writers." (PMID 35449086, 2022). "While in CRC, the ADAR/AZIN1 systems is involved in back-and-forth communication between cancer cells and fibroblasts." (PMID 33671588, 2021). "This is crucial because the data obtained from the TCGA database indicate reduced methylation of the promoter of the gene encoding ADAR and increased methylation in the case of ADARB1 and ADARB2 in cancer tissue compared to non-cancerous tissue." (PMID 41300768, 2025). "Likewise, an apparently inverse impact was seen for other covariates in certain cancers, particularly those of mutA3D/G (most commonly affecting SBS1, SBS44, and ID2) and UV-ADARB1/A3C/ADAR mRNA levels (most commonly affecting SBS10a,b and SBS28)." (PMID 38965255, 2024). "ADAR, which we suggest underpins RNA-SBS1, has been proposed as a tumour suppressor gene that is essential to cancer cells in the context of epigenomic dysfunction owing to its ability to target otherwise immunogenic double-stranded RNAs within short interspersed nuclear elements." (PMID 37046093, 2023). "ADAR is a good therapeutic target for multiple cancers; neither 8-chloroadenosine nor 8-azaadenosine are selective inhibitors of ADAR." (PMID 35586115, 2021). "In line with previous results from other cancer entities, we found that editing directly correlated with ADAR mRNA expression in the IGHV mutated samples, irrespective of the ADAR isoform (p110 or p150) expressed." (PMID 32728184, 2021). "Overall, our data disclose the novel molecular pathway METTL3/ADAR1/CDK2 connecting m6A and ADAR deaminases that can strongly change the scenario of post-transcriptional events with important consequences in cell homeostasis, differentiation, and cancer field." (PMID 33509238, 2021). "Thus, ADAR-recoding can impact the Major Histocompatibility Complex (MHC) ligandome and thereby the specific anti-cancer T-cell response." (PMID 33445472, 2021). "Adding to the complexity of this network, DHX9 helicase which is overexpressed in different types of cancer including ESCC, was found to structurally rearrange ADAR’s RNA-substrates bidirectionally altering the downstream effect of ADAR on AS and exhibiting functional importance in tumorigenicity." (PMID 32708277, 2020). "In this way the RNA editing could be used that target therapeutic resistance and tumor relapse, and also highlights ADAR and CD9 as specific targets for cancer stem cell elimination." (PMID 33215051, 2020). "However, it is increasingly evident that the deregulation of central mediators of editing, such as ADAR and APOBEC proteins across many cancers, suggests that editing contributes to many of the hallmarks of cancer." (PMID 32650588, 2020). "Together, these data support the notion that ADAR knockout can trigger the activation of the IFN-I pathway (MDA5/MAVS-dependent) and the induction of cell lethality (MDA5/MAVS-independent) through distinct upstream mechanisms in cancer cell lines." (PMID 30575730, 2018). "In addition, we did not observe large differences in ADAR expression levels that are consistent with observed editing differences between E and M tumors for all cancer types." (PMID 33106178, 2020).
cancer (continued). "Both “direct” and “indirect” models involving AID/APOBEC and ADAR enzymatic activity, and the information transfer triggering the M2 polarization “switch” may be responsible for generating greater DBD diversity in progressing cancer genomes." (PMID 30802996, 2019). "Although the genomic sequences of the tumor and the healthy cells were not simultaneously available in our study, these SBS could not be attributed to known SNP, catalogued cancer related somatic mutations, and known APOBEC1 or ADAR editing." (PMID 23137041, 2012). "However, a more recent, rigorous study has shown that these adenosine analogs are not actually ADAR inhibitors, suggesting that the previously reported anti-cancer activities may stem from their non-specific cytotoxic effects instead." (PMID 41608661, 2026). "The detection of assumed RNA deaminations at ADAR-targeted WA sites now apparent in genomic DNA thus results from the coupling to cellular reverse transcription (DNA Polymerase eta and now putatively DNA Polymerase theta) at many non-Ig loci across the cancer genome." (PMID 39940758, 2025). "However, previous studies have limited the study of ADAR in BC, and there is no systematic study of its functions, such as its global expression in BC tissues, its location and function in single cancer cells, and its relationship with the tumor microenvironment." (PMID 34616451, 2021). "However, ADAR expression was not consistent with RNA editing differences for some cancer types." (PMID 33106178, 2020). "There is no singular mechanistic basis proposed for the elevated ADAR1 expression; in some cases, there is genomic amplification of the ADAR locus while in other cancers there appears to be an active interferon response with leads to induction of ADAR1 transcript expression." (PMID 32603639, 2020).
tumor (214 papers, 2006 to 2026). "Since ADAR can reduce the toxicity caused by dsRNA accumulation, the increased accumulation of dsRNA undoubtedly increases tumor cell dependence on ADAR." (PMID 40936898, 2025). "Correlation with markers of T cell exhaustion and tumor-associated macrophages further emphasized ADAR’s role in modulating the tumor immune microenvironment." (PMID 40852728, 2025). "In line with this, antitumor immunity was fundamentally increased in mouse models using ADAR-deficient tumor transplants." (PMID 32728184, 2021). "ADAR high expression was significantly associated with metastasis (p = 0.008), stage (p = 0.008), histology (p = 0.015) and size of tumor (p = 0.004)." (PMID 32410589, 2020). "ADAR overexpression and amplification were significantly associated with metastasis, size and stage of tumor." (PMID 32410589, 2020). "The mRNA expression levels of ADAR were positively associated with metastasis, stage, histology and size of tumor." (PMID 32410589, 2020). "This ADAR expression pattern associated with increased incidence of liver cirrhosis and tumor recurrence with shorter disease-free survival times." (PMID 33613561, 2020). "Such variants also exhibit the potential for alternative ADAR targeting preferences during tumor progression." (PMID 27485054, 2016). "ADAR tumor tissue expression was slightly higher among G allele carriers of rs1127313 compared to A allele carriers (P = 0.027)." (PMID 27911851, 2016). "ADAR loss of function leads to an induction of a type I interferon response, which via other therapeutic approaches has been demonstrated to lead to a shift in the tumor environment towards an immune-permissive, anti-tumor state." (PMID 39992915, 2025). "In addition, ADAR is associated with immune-related genes, especially immune checkpoint genes, in the tumor immune microenvironment." (PMID 37414093, 2023). "Based on these results, we believe that the generation of novel miRNA regulatory networks is a critical function of ADAR editing, and, notably, that dysregulated editing may create susceptibilities that allow tumorigenesis and tumor progression to occur." (PMID 30197877, 2018). "In addition, the expression level of ADAR in tumour tissues increased with elevated risk scores." (PMID 40995818, 2025). "Indeed, ADAR amplification was significantly associated with metastasis, stage and size of tumor." (PMID 32410589, 2020). "Besides, overexpression of ADAR was significantly associated with metastasis, stage, histology and size of tumor, which may indicate that ADAR has a pivotal role in stage III to IV progression of GC." (PMID 32410589, 2020). "Supportive of this notion, direct targeting of ADAR in tumor cells is sufficient to induce anti-tumor immunity, lead to tumor cell lethality, and can enhance the anti-tumor response to immune checkpoint blockade." (PMID 39992915, 2025). "For ADAR, reduced expression in tumor tissue was observed in 45.5% of patients, increased expression in 50%, and no change in 4.5%." (PMID 41300768, 2025). "TRIM47 interacted with ADAR to facilitate ADAR protein degradation via ubiquitination, which resulted in the exacerbation of TC tumor expansion, invasion, and metastasis." (PMID 40618019, 2025). "It is likely that ADAR knockout in tumor infiltrating immune cells would have a similar, or perhaps even greater effect, based on the cells’ ability to efficiently produce cytokines." (PMID 39992915, 2025). "Evaluation in preclinical models supports this model in which ADAR targeting in tumor cells can sensitize response to immune checkpoint blockade treatment." (PMID 39992915, 2025). "As we approved, through binding with GSK-3β protein, TRIM47 can enhance ADAR protein stability and ubiquitination so that TRIM47 endorses ADAR-mediated promotion of tumor migration and survival capability." (PMID 40618019, 2025).
tumor (continued). "Then, we further classified samples with ADAR expression between paired tumor and normal tissues into ADAR1-upregulated and -downregulated groups to explore the function of ADAR1 on regulating RNA editing events." (PMID 36895481, 2023). "We found that ADAR mRNA and protein expression was significantly higher in most tumor tissues than in normal tissues." (PMID 37414093, 2023). "Functional analysis revealed significant involvement of ADAR coexpression genes in tumor immune checkpoints in CRC, thereby inducing a proimmunomodulatory effect." (PMID 36660243, 2023). "The evaluation of immune cell infiltration in CRC using the TIMER database revealed strong correlations between ADAR and tumor purity in CRC." (PMID 36660243, 2023). "The correlations of ADAR with infiltrating immune cells (tumor purity) including B cells, CD4+ T cells, CD8+ T cells, neutrophils, macrophages, and dendritic cells in the gastrointestinal tumors were analyzed by TIMER." (PMID 36660243, 2023). "This indicates the complexity of the regulatory mechanisms of the tumor immune microenvironment and the functional diversity of ADAR." (PMID 37414093, 2023). "This evidence indicates the regulatory effect of ADAR on immune cells in the tumor microenvironment." (PMID 37414093, 2023). "In general, the ADAR high expression group had a higher number of immune cells in the tumor microenvironment." (PMID 37414093, 2023). "Enrichment analysis showed that ADAR and its interacting genes were mainly involved in immune and tumor-related pathways such as response to viruses, spliceosome formation and regulatory RNA binding." (PMID 37414093, 2023). "Since ATIRE is mostly mediated by ADARs, in TCGA-LUAD tumour tissues, we observed a significant correlation between the ATIRE risk score and ADAR gene expression (r = 0.24, p < 0.001)." (PMID 36999050, 2023). "The RMPs upregulated in tumours or showing a positive correlation with poor outcomes usually gained more CNVs, such as ADAR, CPSF1, IGF2BP1, and YTHDF1." (PMID 36118888, 2022). "For example, the expression of METTL7A as a tumor suppressor gene can be inhibited by ADAR-mediated RNA editing in the 3′-UTR." (PMID 35559016, 2022). "The increased abundance of ADAR in the mRNA and protein levels in lung tissues of LUAD patients was associated with tumor recurrence." (PMID 36553648, 2022). "ADAR-triggered aberrant RNA editing regulation to promote tumor growth is widely observed in a variety of human solid tumors." (PMID 35964092, 2022). "In LUAD tumours, RNA was shown to be over-edited, and ADAR was abundant at both the mRNA and protein levels." (PMID 34638933, 2021). "The TCGA portal showed that the expression of ADAR in tumor tissues was obviously higher than that in normal tissues." (PMID 34616451, 2021). "ADAR mRNA was significantly overexpressed in the tumor tissues when compared to the adjacent normal tissues (p < 0.01)." (PMID 32410589, 2020). "Among the 42 tumor specimens tested, average expression of ADAR mRNA was significantly upregulated in the tumor tissues when compared to the adjacent normal tissues of the GS patients (p < 0.01)." (PMID 32410589, 2020). "Then, the expression difference of ADAR genes between tumor and normal samples of the ‘edited’ group was measured for each edited loci." (PMID 30911020, 2019). "ADAR-mediated RNA editing may enhance tumor- and immune-related gene activities and pathways in CRC by upregulating PVR expression." (PMID 39126156, 2025). "Understanding this mechanistic duality is essential for developing isoform- and context-specific ADAR-targeted interventions—whether via inhibition of ADAR1’s pro-tumor functions or restoration of ADAR2’s editing activities." (PMID 40852728, 2025). "Dysregulated ADAR activity facilitates carcinogenesis by altering oncogene expression, impairing tumor suppressor pathways, and reprogramming the transcriptome to promote tumor progression." (PMID 40852728, 2025).